MIR548O2 (microRNA 548o-2)
Synonyms: hsa-mir-548o-2
Gene: MicroRNA gene on chromosome 20 (38,516,563 to 38,516,632, forward strand). Ensembl gene ENSG00000275453.
Homologues: Orthologues: chimpanzee MIR548O (100% identical). Paralogues in human: MIR548AH (87% identical), MIR548H3 (87% identical), MIR548S (84% identical), MIR548Z (84% identical), MIR548AJ1 (83% identical), MIR548AN (83% identical), MIR548AX (83% identical), MIR548AY (83% identical), MIR548X2 (81% identical), MIR548AZ (80% identical), MIR548P (79% identical), MIR548AA1 (77% identical), and 13 more.